ADAMTS13 (ADAM metallopeptidase with thrombospondin type 1 motif 13)
Diseases named in the same sentence as ADAMTS13 in open-access papers (continued):
Sharing a sentence is not in itself a finding about the gene and the disease.
thrombotic thrombocytopenic purpura (continued). "Deficiency of ADAMTS13 activity (ADAMTS13:AC) induces the accumulation of UL-VWFMs and leads to platelet hyperaggregation under high shear stress, resulting in thrombotic thrombocytopenic purpura (TTP), a life-threatening blood disease." (PMID 29367644, 2018). "Thrombotic thrombocytopenic purpura (TTP) is caused by the abundance of uncleaved ultralarge von Willebrand factor multimers (ULvWF) due to acquired (autoantibody-mediated) or congenital vWF protease ADAMTS13 deficiency." (PMID 29728803, 2018). "A diagnosis of thrombotic thrombocytopenic purpura (TTP) is confirmed by a severe deficiency (<10%) of a disintegrin and metalloproteinase with a thrombospondin type 1 motif, member 13 (ADAMTS13) activity." (PMID 31249957, 2018). "Yet, most studies about ADAMTS13 have focused on its relationship with VWF or role in thrombotic thrombocytopenic purpura, and limited data are available to corroborate other pathways." (PMID 29615758, 2018). "Force-regulated cleavage of A2 domain of von Willebrand factor (vWF) by ADAMTS13 is a key event in preventing thrombotic thrombocytopenic purpura (TTP)." (PMID 29636514, 2018). "In TMA with acute renal failure, different mechanisms and diseases are possible: Shiga-toxin-induced hemolytic uremic syndrome (HUS), atypical HUS, more rarely thrombotic thrombocytopenic purpura (TTP) with low ADAMTS-13 activity." (PMID 28474317, 2017). "ADAMTS13 deficiency results in an accumulation of UL-VWF and is associated with the development of thrombotic thrombocytopenic purpura (TTP), a life threatening thrombotic microangiopathy." (PMID 25849793, 2015). "ADAMTS13:AC deficiency increases plasma levels of UL-VWFMs, leading to platelet thrombi under high shear stress conditions and resulting in thrombotic thrombocytopenic purpura (TTP)." (PMID 26580395, 2015). "Thrombotic thrombocytopenic purpura (TTP) associated with severe, acquired ADAMTS13 deficiency is an uncommon, acute episodic disorder with risk for relapse." (PMID 25671313, 2015). "Further hematologic workup revealed an ADAMTS13 of 58% (reference range: 68%–163%), eliminating thrombotic thrombocytopenic purpura as an etiology, and plasmapheresis was discontinued." (PMID 25389502, 2014). "TAMOF is characterized as a thrombotic microangiopathic process, similar to that described in thrombotic thrombocytopenic purpura (TTP), which is characterized by decreased ADAMTS13 protease activity causing accumulation of large, multimeric von Willebrand Factor (vWF)." (PMID 24408224, 2014). "Thrombotic microangiopathies can be associated with defective regulation of the AP (atypical hemolytic-uremic syndrome) or with inadequate cleavage by ADAMTS-13 of ULVWF multimeric strings secreted by/anchored to ECs (thrombotic thrombocytopenic purpura)." (PMID 23555663, 2013). "Deficient proteolysis of ULvWF (ultra large von Willebrand factor) due to reduced ADAMTS-13 activity results in disseminated platelet-rich thrombi in the microcirculation characteristic of thrombotic thrombocytopenic purpura." (PMID 23537039, 2013). "Deficient ADAMTS13 activity leads to thrombotic thrombocytopenic purpura (TTP) which may either be the result of mutations in the ADAMTS13 gene (congenital TTP) or due to the presence of auto-antibodies against ADAMTS13 (acquired TTP)." (PMID 21720563, 2011). "Deficiency of ADisintegrin And Metalloprotease with Thrombospondin (ADAMTS13) results in thrombotic thrombocytopenic purpura (TTP)." (PMID 21774770, 2011). "The zinc metalloprotease ADAMTS13 is a multidomain protein that cleaves von Willebrand Factor (VWF) and is implicated in Thrombotic Thrombocytopenic Purpura (TTP) pathogenesis." (PMID 19654870, 2009).
thrombotic thrombocytopenic purpura (continued). "Thrombotic thrombocytopenic purpura (TTP) is a rare but potentially fatal hematologic emergency characterized by the formation of microvascular platelet-rich thrombi due to a severe deficiency of ADAMTS13 (a disintegrin and metalloproteinase with thrombospondin type 1 motif, member 13)." (PMID 40827194, 2025). "Thrombotic thrombocytopenic purpura (TTP) is a rare and life-threatening blood disease caused by severe deficiency of a disintegrin and metalloprotease with thrombospondin type I repeats-13 (ADAMTS-13) enzyme, a von Willebrand factor (VWF)-cleaving protease." (PMID 40034892, 2025). "Unlike thrombotic thrombocytopenic purpura, which results from severe ADAMTS13 deficiency, aHUS is driven by uncontrolled activation of the alternative complement pathway." (PMID 40217974, 2025). "We report a case of a patient with systemic lupus erythematosus (SLE) who presented with encephalopathy and was subsequently diagnosed with thrombotic thrombocytopenic purpura (TTP) based on ADAMTS13 (a disintegrin and metalloproteinase with thrombospondin motifs 13) deficiency." (PMID 40625480, 2025). "In addition, the United States Food and drug administration approved the first and only recombinant ADAMTS-13 enzyme replacement therapy for the treatment of congenital thrombotic thrombocytopenic purpura." (PMID 38473925, 2024). "Thrombotic thrombocytopenic purpura (TTP) is a thrombotic microangiopathy caused by a severe functional deficiency in a disintegrin and metalloprotease with thrombospondin type I repeats-13 (ADAMTS13), the specific von Willebrand factor (VWF)-cleaving protease." (PMID 37176509, 2023). "Thrombotic thrombocytopenic purpura (TTP) is a rare, though severe, inherited or acquired disease caused by severe deficiency of the Von Willebrand factor-cleaving serine protease, ADAMTS-13 (a disintegrin and metalloproteinase with a thrombospondin type 1 motif, member 13)." (PMID 36709264, 2023). "Thrombotic thrombocytopenic purpura (TTP) is a rare and potentially life-threatening blood disorder caused by a deficiency or dysfunction of ADAMTS13 and can occur secondary to various conditions, including autoimmune diseases, infections, medications, pregnancy, and malignancies." (PMID 37223178, 2023). "Severe deficiency plasma ADAMTS13 activity may lead to increased size of VWF multimers and increased risk of microvascular thrombosis such as thrombotic thrombocytopenic purpura." (PMID 36362664, 2022). "ADAMTS13 belongs to the ADAMTS family, deficiency of which could lead to thrombotic thrombocytopenic purpura." (PMID 35011462, 2021). "Thrombotic thrombocytopenic purpura (TTP) is a life-threatening disease due to a quantitative or qualitative defect in ADAMTS13 resulting in the increased presence of ULVWF, finally resulting in severe thrombotic events such as systemic platelet aggregation, organ ischemia." (PMID 33919627, 2021). "Some studies have reported that increased ADAMTS13 levels are risk factors for various diseases such as diabetes, preeclampsia, liver cirrhosis, and thrombotic thrombocytopenic purpura because of the imbalance between ADAMTS13 and von Willebrand factor (VWF) levels in circulation." (PMID 34276770, 2021). "However, nephrological disorders have been described, as thrombotic microangiopathy (TMA), whose most frequent forms are thrombotic thrombocytopenic purpura (TTP) characterized by an insufficient ADAMTS13 activity and hemolytic uremic syndrome (HUS)." (PMID 33325640, 2021). "Thrombotic thrombocytopenic purpura (TTP) is a thrombotic microangiopathy (TMA) characterized by microangiopathic hemolytic anemia and thrombocytopenia developed due to deficiency of ADAMTS13 (a disintegrin and metalloprotease with thrombospondin type 1 repeats, member 13)." (PMID 33161686, 2021).
thrombotic thrombocytopenic purpura (continued). "Thrombotic thrombocytopenic purpura (TTP) is a rare blood disorder caused by the absence of the specific proteolytic activity of ADAMTS-13 toward the von Willebrand factor, which causes clots in small vessels throughout the whole body." (PMID 32150898, 2020). "Her ADAMTS13 level was normal, effectively excluding thrombotic thrombocytopenic purpura." (PMID 33203373, 2020). "ADAMTS13 activity level was decreased at 32% (normal is greater than 67%) but did not meet thrombotic thrombocytopenic purpura's (TTP) diagnostic criteria (below 5%‐10%)." (PMID 33363792, 2020). "Thus, deficiency of ADAMTS13 leads to Thrombotic Thrombocytopenic Purpura (TTP), which is a thrombotic microangiopathy caused either by the development of autoantibodies against ADAMTS13 (acquired TTP) or by mutations in the ADAMTS13 gene." (PMID 32365113, 2020). "Promising agents under evaluation for micro-thrombosis secondary to thrombotic thrombocytopenic purpura include, caplacizumab (an inhibitor of the glycoprotein-Ib/IX-Von-Willebrand factor axis), N-acetyl cysteine, recombinant ADAMTS13, and anti-plasmocyte compounds." (PMID 31741612, 2019). "Normal ADAMTS13 levels as well as negative culture and serology for Shiga-toxin excluded, respectively, thrombotic thrombocytopenic purpura (TTP) and typical HUS caused by Shiga toxin-producing Escherichia coli (STEC-HUS)." (PMID 31360562, 2019). "It is well-established that the presence of shiga toxin in typical HUS, complement abnormalities in aHUS, or ADAMTS13 deficiency in thrombotic thrombocytopenic purpura (TTP) are necessary but not sufficient in themselves to trigger TMA." (PMID 30619356, 2018). "Thrombotic thrombocytopenic purpura was less likely with adequate ADAMTS13." (PMID 28774273, 2017). "Two major variants of TMA are hemolytic uremic syndrome (HUS) caused by Shiga toxin and thrombotic thrombocytopenic purpura (TTP) associated with decreased activity of a disintegrin-like and metalloproteinase with thrombospondin type 1 motifs member 13 (ADAMTS13])." (PMID 27399110, 2016). "A more common TMA is thrombotic thrombocytopenic purpura, which is caused by the lack of normal ADAMTS-13-mediated cleavage of von Willebrand factor (VWF)." (PMID 23991205, 2013). "Severe deficiency of ADAMTS13 is associated with thrombotic thrombocytopenic purpura, but does not always correlate with its clinical course." (PMID 21909423, 2011). "Search terms included "pregnancy", "thrombotic thrombocytopenic purpura", "hereditary TTP", "acquired TTP", "ADAMTS13," "thrombotic microangiopathy," "HELLP," "postpartum", and "complement-mediated TMA" alone or in combination." (PMID 41751340, 2026). "Hereditary thrombotic thrombocytopenic purpura (TTP) is a rare autosomal recessive inherited disease caused by an ADAMTS1 gene mutation, resulting in absence or severe deficiency of plasma ADAMTS13 activity." (PMID 41797737, 2026). "This further supported a diagnosis of TMA rather than thrombotic thrombocytopenic purpura (TTP), given that ADAMTS13 activity in TTP is usually less than 10%." (PMID 41281070, 2025). "TPE also gives the possibility to replenish deficient factors like clotting factors or replacing plasma components as in thrombotic thrombocytopenic purpura (TTP) (ADAMTS13)." (PMID 41010348, 2025). "Among these, 50 patients exhibited ADAMTS-13 activity ≤ 10%, confirming a diagnosis of thrombotic thrombocytopenic purpura (TTP)." (PMID 40993743, 2025). "Timely diagnosis of thrombotic thrombocytopenic purpura (TTP) remains challenging due to its rarity, clinical heterogeneity, and reliance on delayed ADAMTS13 assays." (PMID 41179877, 2025). "Acquired thrombotic thrombocytopenic purpura (TTP) occurs when anti-ADAMTS13 autoantibodies form and decrease serum levels of ADAMTS13, a protease that cleaves von Willebrand factor." (PMID 39963616, 2025).
thrombotic thrombocytopenic purpura (continued). "Hexachloroethane, a halogenated hydrocarbon (p = 0.001964), exhibited an enrichment profile highly consistent with ADAMTS13’s known role in thrombotic thrombocytopenic purpura (TTP)." (PMID 41283645, 2025). "Laboratory findings showed reduced a disintegrin-like and metalloproteinase with thrombospondin type 1 motif 13 (ADAMTS13) activity with the presence of ADAMTS13 inhibitor, confirming immune thrombotic thrombocytopenic purpura (TTP)." (PMID 40091942, 2025). "On POD 3, ADAMTS13 activity results indicated 75%, effectively excluding thrombotic thrombocytopenic purpura (TTP)." (PMID 40704245, 2025). "In other words, in human endothelial cells the viral S protein evokes a disbalance in the vWF:ADAMTS-13 ratio which may favor thrombi formation, similar to that observed in certain pro-coagulant and pro-thrombotic conditions such as thrombotic thrombocytopenic purpura or stroke." (PMID 38225643, 2024). "The patient tested positive for ADAMTS-13 antibodies and was diagnosed with thrombotic thrombocytopenic purpura (TTP)." (PMID 38233944, 2024). "Thrombotic thrombocytopenic purpura (TTP) is a disorder of endothelial dysfunction characterized by autoantibodies inhibiting the metalloprotease ADAMTS-13." (PMID 39969357, 2024). "Thrombotic thrombocytopenic purpura (TTP) was excluded because of the presence of normal ADAMTS13 activity." (PMID 39062862, 2024). "The interplay between vWF and ADAMTS13 are crucial in the pathogenesis of thrombotic microangiopathy such as thrombotic thrombocytopenic purpura (TTP)." (PMID 38069327, 2023). "Thrombotic thrombocytopenic purpura (TTP) is a potentially life-threatening, rare acute thrombotic microangiopathy (TMA), caused by a severe ADAMTS13 deficiency." (PMID 37489376, 2023). "The determination of ADAMTS-13 activity enables discriminating thrombotic thrombocytopenic purpura (TTP) from other forms of TMA." (PMID 35927768, 2022). "Intense deficiency of ADAMTS-13 results in accumulation of ultra-large VWF multimers and causes microvascular thrombosis, thrombocytopenia and thrombotic thrombocytopenic purpura (TTP)." (PMID 36128671, 2022). "Our review suggests that due to many overlapping clinical and laboratory features thrombotic thrombocytopenic purpura may be erroneously diagnosed in sickle cell disease instead of other complications such as fat embolism syndrome and confirmation with ADAMTS13 testing is essential." (PMID 36431152, 2022). "Thrombotic thrombocytopenic purpura (TTP) is caused by the deficiency of ADAMTS13, a von Willebrand factor cleaving protease, which results in thrombotic microangiopathy." (PMID 36185943, 2022). "Plasma ADAMTS-13 activity was normal, and anti-ADAMTS-13 antibodies were undetected, thereby excluding thrombotic thrombocytopenic purpura (TTP)." (PMID 34248927, 2021). "Thrombotic thrombocytopenic purpura (TTP) is defined as decreased von Willebrand factor cleaving protease (a disintegrin-like and metalloproteinase with thrombospondin type 1 motifs 13; ADAMTS13) activity." (PMID 32571244, 2020). "Graves' disease (GD) and thrombotic thrombocytopenic purpura (TTP) are autoimmune diseases caused by autoantibodies against the TSH receptor (TRAb) and the enzyme ADAMTS13." (PMID 30159177, 2018). "Patients with PPS lack proper glucosylation on TSR containing proteins; however, they do not display features associated with a total loss of function of many proteins modified by B3GLCT, e.g. PPS patients do not display ADAMTS13 deficiency (Thrombotic thrombocytopenic purpura)." (PMID 28926587, 2017). "We report the case of a 61-year-old man living in Reunion Island who suffered from toxocariasis with significant liver involvement associated with an autoimmune thrombotic thrombocytopenic purpura (TTP) due to the presence of anti-ADAMTS13 autoantibodies." (PMID 28727752, 2017).
thrombotic thrombocytopenic purpura (continued). "It is the presence of these “ultra large” VWF multimers, caused by ADAMTS13 deficiency, that initiates the formation VWF-platelet microthrombi, which characterize thrombotic thrombocytopenic purpura (TTP)." (PMID 28209710, 2017). "ITP and thrombotic thrombocytopenic purpura (TTP) are distinct diseases that are differentially diagnosed by measuring the serum ADAMTS13 concentration." (PMID 25274611, 2014). "Deficiency of plasma ADAMTS13 activity could result in an accumulation of newly released ultra large (UL) VWF on endothelial cells where it is synthesized and in blood, leading to a potentially fatal syndrome, thrombotic thrombocytopenic purpura (TTP)." (PMID 24790789, 2013). "ADAMTS13 is of immense therapeutic interest because it is the target gene in thrombotic thrombocytopenic purpura (TTP)." (PMID 24213506, 2012). "This is important given that ULVWF multimers freshly secreted from endothelial cells are accumulated in plasma due to impaired cleavage by ADAMTS13, as seen in patients with thrombotic thrombocytopenic purpura (TTP)." (PMID 21490767, 2011). "The normal ADAMTS13 activity excluded thrombotic thrombocytopenic purpura (TTP)." (PMID 40823568, 2025). "Microangiopathies such as thrombotic thrombocytopenic purpura, caused by ADAMTS13 deficiency, leading to microangiopathic hemolytic anemia and thrombocytopenia with neurological symptoms, renal impairment, and schistocytes on a blood smear, can be ruled out using the ADAMTS13 activity assay." (PMID 40922302, 2025). "However, an ADAMTS13 activity level of 48 IU/dL made thrombotic thrombocytopenic purpura (TTP) unlikely." (PMID 41181789, 2025). "Diagnosis is based on the triad of AKI, microangiopathic anemia and thrombocytopenia, but requires exclusion of other TMAs—such as typical HUS and thrombotic thrombocytopenic purpura (TTP)—via stool cultures and ADAMTS13 activity testing." (PMID 41333025, 2025). "Congenital or acquired defects in ADAMTS-13 are associated with enhancement in large VWF multimers, bringing about the formation of platelet-rich plugs and systemic microthrombosis, a condition called thrombotic thrombocytopenic purpura (TTP)." (PMID 38327640, 2024). "The association of DIC and low ADAMTS13 activity may have contributed to the severity of microthrombotic complications, even in the absence of thrombotic microangiopathy as thrombotic thrombocytopenic purpura (TTP) or pneumococcal-associated haemolytic uremic syndrome (pa-HUS)." (PMID 37159753, 2023). "The last two decades have been marked by the connection between an old disease, the thrombotic thrombocytopenic purpura (TTP), and a protein ADAMTS13 (the 13th member of the ADAMTS protein family)." (PMID 36513992, 2022). "However, PE also has beneficial effects for infusing useful plasma components, such as a disintegrin-like and metalloprotease with thrombospondin type-1 motifs-13 (ADAMTS-13) in thrombotic thrombocytopenic purpura (TTP)." (PMID 35723077, 2022). "Severe deficiency of plasma ADAMTS-13 activity, primarily resulting from acquired autoantibodies against ADAMTS-13, may lead to a potentially fatal syndrome thrombotic thrombocytopenic purpura (TTP)." (PMID 36852110, 2022). "Thrombotic thrombocytopenic purpura (TTP) is a thrombotic microangiopathy (TMA) caused by decreased activity of a disintegrin and metalloproteinase with a thrombospondin type 1 motif, member 13 (ADAMTS13)." (PMID 35989829, 2022). "As ADAMTS13 (a disintegrin-like and metalloproteinase with thrombospondin type 1 motifs 13) activity was absent and the ADAMTS13 inhibitor was detected, she was diagnosed with acquired thrombotic thrombocytopenic purpura (TTP)." (PMID 35735738, 2022). "The ultimate diagnosis of thrombotic thrombocytopenic purpura (TTP) is a rare but life-threatening condition which is typically hallmarked by thrombotic microangiopathy (TMA) and dysfunctional ADAMTS13 enzymatic activity." (PMID 37465548, 2021).